VPS8 (VPS8 subunit of CORVET complex)
Description:
Plays a role in vesicle-mediated protein trafficking of the endocytic membrane transport pathway. Believed to act as a component of the putative CORVET endosomal tethering complexes which is proposed to be involved in the Rab5-to-Rab7 endosome conversion probably implicating MON1A/B, and via binding SNAREs and SNARE complexes to mediate tethering and docking events during SNARE-mediated membrane fusion. The CORVET complex is proposed to function as a Rab5 effector to mediate early endosome fusion probably in specific endosome subpopulations. Functions predominantly in APPL1-containing endosomes.
Synonyms: KIAA0804; FLJ32099
Tractability: PROTAC: ubiquitination databases record sites on it; its protein half-life has been measured.
Gene: Protein-coding gene on chromosome 3 (184,812,113 to 185,054,009, forward strand). Ensembl gene ENSG00000156931.
Subcellular location: Early endosome
Gene Ontology:
Molecular function: protein binding; protein-membrane adaptor activity
Biological process: endosomal vesicle fusion; regulation of SNARE complex assembly; protein targeting to vacuole
Cellular component: early endosome; CORVET complex; late endosome; endosome
Genetic constraint (gnomAD): Loss-of-function variants: 89 observed, 154.19 expected, observed/expected ratio (o/e) 0.58, 90% interval 0.49 to 0.69. The upper end of that interval is the gene's LOEUF score, 0.69, which puts it in group 2 of 6, group 1 being the genes least tolerant of losing a copy. Missense variants: 1,247 observed, 1,373.1 expected, observed/expected ratio (o/e) 0.91, 90% interval 0.87 to 0.95. Synonymous variants: 493 observed, 472.58 expected, observed/expected ratio (o/e) 1.04, 90% interval 0.97 to 1.12.
Gene-disease validity (ClinGen):
ClinGen rates the evidence that VPS8 causes each of these diseases.
arthrogryposis multiplex congenita (autosomal recessive): Limited. Arthrogryposis multiplex congenita (AMC) is a group of disorders characterized by congenital limb contractures.
Homologues: Orthologues: chimpanzee VPS8 (99% identical), macaque VPS8 (99% identical), dog VPS8 (97% identical), pig VPS8 (97% identical), rabbit VPS8 (96% identical), rat Vps8 (94% identical), mouse Vps8 (93% identical), guinea pig VPS8 (93% identical), tropical clawed frog vps8 (76% identical), zebrafish vps8 (68% identical), Drosophila melanogaster Vps8 (29% identical), Caenorhabditis elegans vps-8 (22% identical). Paralogues in human: WDR72 (14% identical), RBBP5 (8% identical).
Diseases named in the same sentence as VPS8 in open-access papers:
VPS8 is named in the same sentence as 5 diseases in open-access papers, as found by Europe PMC text mining. Sharing a sentence is not in itself a finding about the gene and the disease. The quoted sentences say what the papers report.
atherosclerosis (1 paper, 2022). A disease characterized by the build-up of fatty material and calcium deposition in the arterial wall resulting in partial or complete occlusion of the arterial lumen. "The VPS8 gene (along with VPS3) has been reported to regulate integrin in recycling endosomes, which, in a dysfunctional state, may cause several cardiac ailments and atherosclerosis." (PMID 36553589, 2022).
Insulin resistance (1 paper, 2020). Increased resistance towards insulin, that is, diminished effectiveness of insulin in reducing blood glucose levels. "The induction of VPS8, POLRMT, and IGFBP5 GPs at the end of 4th week during 4-week intermittent fasting preceded the significant reduction in insulin resistance estimated by HOMA-IR that occurred 1 week after 4-week intermittent fasting." (PMID 33110154, 2020).
malaria (1 paper, 2025). Malaria is a serious and sometimes fatal disease caused by a parasite that commonly infects a certain type of mosquito which feeds on humans. "Homologues for the CORVET and HOPS specific subunits VPS8 and VPS41 are not currently annotated in the malaria genome, but BLAST analysis using the VPS 41/8 domain of Tgvps8 as query identified a conserved gene with unknown function (PF3D7_0916400) sharing 48% identity." (PMID 40198740, 2025).
tumor (1 paper, 2016). "As the semilethality, the increased blood cell number and melanotic tumor formation are all rescued by the Vps8-HA transgene, these indicate that our reporter is functional, and that the observed phenotypes are solely due to the loss of Vps8 function." (PMID 27253064, 2016). "Importantly, double mutants of vps8 and lt are similar to vps8 mutants regarding tumor formation." (PMID 27253064, 2016).
VPS8 also shares sentences with these, for which no sentence is quoted: diabetes (1 paper).